CD5 (CD5 molecule)
Description:
Lymphoid-specific receptor expressed by all T-cells and in a subset of B-cells known as B1a cells. Plays a role in the regulation of TCR and BCR signaling, thymocyte selection, T-cell effector differentiation and immune tolerance. Acts by interacting with several ligands expressed on B-cells such as CD5L or CD72 and thereby plays an important role in contact-mediated, T-dependent B-cell activation and in the maintenance of regulatory T and B-cell homeostasis. Functions as a negative regulator of TCR signaling during thymocyte development by associating with several signaling proteins including LCK, CD3Z chain, PI3K or CBL. Mechanistically, co-engagement of CD3 with CD5 enhances phosphorylated CBL recruitment leading to increased VAV1 phosphorylation and degradation. Modulates B-cell biology through ERK1/2 activation in a Ca(2+)-dependent pathway via the non-selective Ca(2+) channel TRPC1, leading to IL-10 production.
Synonyms: LEU1; T1
Tractability: Small molecule: it has a binding pocket of medium quality. Antibody: its Gene Ontology location is reachable by antibodies, with high confidence; UniProt places it where antibodies can reach, with medium confidence; UniProt predicts a signal peptide or a membrane-spanning region. PROTAC: ubiquitination databases record sites on it. Other modalities: a drug acting on it is in phase 2 or 3 trials.
Gene: Protein-coding gene on chromosome 11 (61,102,489 to 61,127,852, forward strand). Ensembl gene ENSG00000110448.
Subcellular location: Cell membrane
Gene Ontology:
Molecular function: protein binding; signaling receptor activity
Biological process: negative regulation of B cell receptor signaling pathway; cell recognition; T cell costimulation
Cellular component: plasma membrane; external side of plasma membrane; membrane
Genetic constraint (gnomAD): Loss-of-function variants: 35 observed, 55.59 expected, observed/expected ratio (o/e) 0.63, 90% interval 0.48 to 0.83. The upper end of that interval is the gene's LOEUF score, 0.83, which puts it in group 3 of 6, group 1 being the genes least tolerant of losing a copy. Missense variants: 533 observed, 625.17 expected, observed/expected ratio (o/e) 0.85, 90% interval 0.79 to 0.92. Synonymous variants: 228 observed, 256.58 expected, observed/expected ratio (o/e) 0.89, 90% interval 0.8 to 0.99.
Homologues: Orthologues: chimpanzee CD5 (99% identical), macaque CD5 (90% identical), rabbit CD5 (70% identical), pig CD5 (69% identical), dog CD5 (69% identical), mouse Cd5 (64% identical), rat Cd5 (63% identical), guinea pig CD5 (60% identical), zebrafish si:dkey-14d8.20 (20% identical), Drosophila melanogaster Loxl2 (10% identical), zebrafish si:ch211-150o23.3 (8% identical). Paralogues in human: DMBT1 (26% identical), CD163 (24% identical), CD163L1 (23% identical), SSC5D (22% identical), SCART1 (20% identical), PRSS12 (19% identical), LOXL3 (19% identical), LOXL4 (19% identical), LOXL2 (18% identical), SSC4D (18% identical), CD6 (17% identical), CD5L (12% identical), and 3 more.
Diseases named in the same sentence as CD5 in open-access papers:
CD5 is named in the same sentence as 281 diseases in open-access papers, as found by Europe PMC text mining. Sharing a sentence is not in itself a finding about the gene and the disease. The quoted sentences say what the papers report.
Chronic lymphocytic leukemia (238 papers, 2007 to 2026). "Diminished expression of surface CD5 (sCD5) is associated with several pathological conditions, including systemic lupus erythematosus, multiple sclerosis, B-cell chronic lymphocytic leukemia, and T-cell acute lymphoblastic leukemia (T-ALL)." (PMID 40788503, 2025). "CD5 encodes the CD5 protein, expressed in T cells, B1a cells, chronic lymphocytic leukemia cells, and dendritic cells." (PMID 41009814, 2025). "Chronic lymphocytic leukemia (CLL) is defined by a marked increase in dysfunctional CD5+CD19+CD23+ B cells, which is caused by irregular cell proliferation and apoptosis." (PMID 39524849, 2024). "The accumulation of mature-appearing CD19+ CD23+ CD5+ B cells in the bone marrow, peripheral blood, and lymphoid organs is a hallmark of chronic lymphocytic leukemia (CLL), an indolent B-cell cancer." (PMID 37830606, 2023). "Chronic lymphocytic leukemia (CLL) is defined as a slow-developing disease caused by a peripheral accumulation of CD5+ B lymphocytes in the peripheral blood, bone marrow, and secondary lymphoid organs." (PMID 37760777, 2023). "Chronic lymphocytic leukemia/small lymphocytic lymphoma (CLL/SLL) develops from small mature CD5+ and CD23+ B-cells with mutated or unmutated IGHV genes." (PMID 36358737, 2022). "Chronic lymphocytic leukemia (CLL) is characterized as a slow developing disease caused by the clonal accumulation of CD5+ B lymphocytes in the bone marrow, which eventually extends into the blood and secondary lymphoid organs." (PMID 31878283, 2019). "In fact, CD5 is an important diagnostic marker of chronic lymphocytic leukemia/small lymphocytic lymphoma (CLL/SLL) and mantle cell lymphoma." (PMID 31644584, 2019). "Chronic lymphocytic leukemia (CLL) is a monoclonal disorder characterized by an increase in the number of functionally deficient mature CD5+ B lymphocytes in the blood, bone marrow, lymph nodes, and spleen." (PMID 26316479, 2015). "Despite the shared pattern of surface antigens, neoplastic cells in chronic lymphocytic leukemia (CLL) are highly heterogeneous in CD5 expression, a marker linked to a proliferative pool of neoplastic cells." (PMID 32802894, 2020). "Lastly, the malignant clone originally co-expressed CD5, a hallmark of classic chronic lymphocytic leukemia; the loss of CD5 expression that occurred, in this case, suggests that the patient’s lymphoproliferative disorder may have been an atypical form of chronic lymphocytic leukemia." (PMID 26858922, 2015). "Flow cytometry confirmed a dominant clonal population consistent with classical HCL, along with a small CD5+/CD23+ monoclonal B-cell population compatible with a chronic lymphocytic leukemia-like clone." (PMID 41497420, 2026). "Flow cytometry of peripheral blood further revealed a dominant monoclonal B-cell population immunophenotypically consistent with classical HCL and a smaller CD5+/CD23+ kappa-restricted clone compatible with a chronic lymphocytic leukemia (CLL)-like population." (PMID 41497420, 2026). "Chronic lymphocytic leukaemia (CLL) is a malignancy of mature CD5+ B lymphocytes that accumulate in the blood, bone and secondary lymphoid tissues." (PMID 40721481, 2025). "Chronic lymphocytic leukemia is diagnosed by the presence of mature B lymphocytes in the peripheral blood and characterized by B cell markers and the CD5 antigen, with a count exceeding 5000/mm3 and fewer than 55% prolymphocytes." (PMID 40150071, 2025). "Chronic lymphocytic leukemia/small lymphocytic lymphoma (CLL/SLL) is a lymphoproliferative syndrome characterized by small monomorphic CD19+ B-cells that frequently co-express CD5, CD23, and CD200, with weak CD20 and surface immunoglobulin expression." (PMID 41149470, 2025). "Chronic lymphocytic leukemia (CLL) is a clonal neoplasia defined by the presence of blastic cells consisting of CD5+ mature B lymphocytes in the peripheral circulation." (PMID 40150071, 2025).
Chronic lymphocytic leukemia (continued). "The differential diagnoses among CD5-positive B-cell neoplasms include mainly chronic lymphocytic leukemia/small lymphocytic lymphoma (CLL/SLL) (example), mantle cell lymphoma (MCL) (example) and (rarely) marginal zone lymphoma (MZL)." (PMID 40075660, 2025). "Chronic lymphocytic leukemia (CLL) and small lymphocytic lymphoma (SLL) are characterized by the clonal expansion of mature small CD5+ B-cells and represent different manifestations of the same disease." (PMID 40430009, 2025). "Chronic lymphocytic leukemia (CLL) is a B lymphoid neoplasm characterized by the monoclonal expansion of CD19+ CD5+ positive cells in blood, bone marrow, and lymphoid tissues." (PMID 39273202, 2024). "Chronic lymphocytic leukemia is characterized by the accumulation of malignant CD5+CD19+ B cells in peripheral blood, bone marrow, and secondary lymphoid organs." (PMID 38540350, 2024). "Chronic Lymphocytic Leukemia (CLL) is characterized by a progressive accumulation of monoclonal CD5+/CD19+/IgMlow/IgDlow mature B-cells in the blood, bone marrow, lymph nodes and spleen, with an increased resistance to apoptosis and a low proliferation rate." (PMID 38918490, 2024). "Chronic lymphocytic leukemia (CLL) is characterized by the accumulation of CD5+ B cells in lymphoid tissues." (PMID 39594776, 2024). "Chronic lymphocytic leukemia (CLL) is an incurable progressive malignancy of CD5+ B cells with a birth rate between 0.1% and 1% of the entire clone per day." (PMID 39691453, 2024). "Chronic lymphocytic leukemia (CLL) is characterized by the accumulation of neoplastic CD5+/CD19+ B lymphocytes in the blood." (PMID 39796700, 2024). "Chronic lymphocytic leukemia (CLL) is a low-grade lymphoproliferative neoplasm characterized by the accumulation of clonal B-cells expressing CD5, CD19, CD20(dim), and CD23 in the lymphoid organs and blood." (PMID 39123460, 2024). "B-cell chronic lymphocytic leukemia (CLL) is characterized by aberrant accretion of mature clonal CD5+ B lymphocytes in the blood, bone marrow and lymphoid tissues." (PMID 38571491, 2024). "Chronic lymphocytic leukemia (CLL) is characterized by an expansion of malignant CD5+ B cells in the peripheral blood (PB), bone marrow (BM), and secondary lymphoid tissues." (PMID 39691453, 2024). "Chronic lymphocytic leukemia (CLL) is a disease characterized by the expansion of a CD5+ B cell clone in the peripheral blood, bone marrow (BM), and secondary lymphoid tissues." (PMID 37007084, 2023). "Chronic lymphocytic leukemia is a lymphoproliferative disorder marked by the expansion of monoclonal, mature CD5+CD23+ B cells in peripheral blood, secondary lymphoid tissues, and bone marrow." (PMID 38258066, 2023). "Exceptional LBCL, IRF4+ cases with CD5 or CD23 expression need to be distinguished from prolymphocytic progression or large cell transformation of chronic lymphocytic leukemia/small lymphocytic lymphoma." (PMID 37081786, 2023). "Chronic lymphocytic leukaemia (CLL) is a haematological malignancy characterised by the accumulation of monoclonal mature B lymphocytes (positive for CD5+ and CD23+) in peripheral blood, bone marrow, and lymph nodes." (PMID 36900108, 2023). "Chronic lymphocytic leukemia (CLL) is a B cell malignancy characterized by the accumulation of clonal CD19+ CD5+ malignant B cells in the blood, bone marrow, and secondary lymphoid organs." (PMID 38111528, 2023). "Chronic lymphocytic leukemia (CLL) is characterized by the accumulation of B lymphocytes aberrantly expressing CD5+ in peripheral blood, bone marrow, and secondary lymphoid organs (lymph nodes and spleen)." (PMID 38137005, 2023). "Chronic lymphocytic leukemia (CLL) is characterized by the accumulation of CD19+ CD5+ clonal B lymphocytes in the blood, bone marrow, and peripheral lymphoid organs." (PMID 38111528, 2023).
Chronic lymphocytic leukemia (continued). "Chronic lymphocytic leukemia (CLL) is a B-cell malignancy characterized by the accumulation of CD5+ B cells in the peripheral blood (PB), bone marrow (BM), and lymph nodes (LNs)." (PMID 37958334, 2023). "One was B small lymphoid cell lymphoma/chronic lymphocytic leukemia: the expression rates of CD5, CD23, CD20, and CD79a were 100%, and the Ki67 index was ≥40%." (PMID 35242496, 2022). "Chronic lymphocytic leukemia (CLL) is a malignancy of CD5+ B cells and characterized by the accumulation of small, mature-appearing lymphocytes in the bone marrow, blood, and lymphoid tissues." (PMID 35784717, 2022). "Chronic lymphocytic leukemia (CLL) is characterized by the clonal expansion of CD5+ and CD23+ B lymphocytes in the circulation, peripheral lymphoid organs and bone marrow." (PMID 36430731, 2022). "Chronic lymphocytic leukemia (CLL) is characterized by the accumulation of CD5+ B cells in blood, secondary lymphoid organs and bone marrow." (PMID 35875135, 2022). "Chronic lymphocytic leukemia—CLL—is a malignant clonal proliferative disorder of mature CD5+ B lymphocytes that accumulate within the peripheral blood, lymphoid tissues, and bone marrow." (PMID 35204649, 2022). "Chronic Lymphocytic Leukemia (CLL) is characterized by the accumulation of monoclonal B lymphocytes expressing CD5, CD23, and low surface immunoglobulin in blood, bone marrow, and lymphoid tissues." (PMID 35837088, 2022). "B cell CLL (>95% of cases) is characterised by clonal expansion and accumulation of immature CD5+/CD19+ B cells in the bone marrow and lymph nodes, where oncogenesis is believed to be driven by microenvironment signals, and in the peripheral blood." (PMID 35563051, 2022). "Such examples include CD19/CD5 dual positivity for diagnosis of chronic lymphocytic leukaemia or CD19/CD10+ dual positivity for a common acute lymphoblastic leukaemia." (PMID 35937760, 2022). "Chronic Lymphocytic Leukemia (CLL) arises from the clonal expansion of CD5+ B lymphocytes in the BM." (PMID 36304465, 2022). "We herein report an innovative antisense approach based on Peptide Nucleic Acids (PNAs) to down-modulate CD5 expression levels in chronic lymphocytic leukemia (CLL)." (PMID 35358273, 2022). "CD5 positivity in B-cell lymphoproliferative disorders (LPD) is usually considered characteristic of chronic lymphocytic leukemia or mantle cell lymphoma." (PMID 36032099, 2022). "Chronic lymphocytic leukemia (CLL) is characterized by clonal proliferation of mature CD5-positive B-cells that accumulate in the blood and lymphoid organs." (PMID 35523865, 2022). "Chronic lymphocytic leukemia (CLL) is a lymphoproliferative disease characterized by the accumulation of CD5+ CD19+ malignant B cells." (PMID 35804817, 2022). "Chronic lymphocytic leukemia (CLL) is a hematological neoplasm that is characterized by the expansion of CD5-, CD19-positive mature-appearing monoclonal B lymphocytes in the blood, bone marrow, and lymph nodes, which are resistant to apoptosis." (PMID 36209148, 2022). "Chronic lymphocytic leukemia (CLL) is characterized by the accumulation of long-lived mature CD5+ B cells in blood, bone marrow and secondary lymphoid organs." (PMID 35847884, 2022). "Chronic lymphocytic leukemia (CLL) is an indolent heme malignancy characterized by the accumulation of CD5+ CD19+ B cells and episodes of relapse." (PMID 34187466, 2021). "Monoclonal B cell lymphocytosis (MBL) and chronic lymphocytic leukemia (CLL) are lymphoproliferative disorders characterized by the presence of abnormal numbers of CD5+ monoclonal B lymphocytes in the blood or tissues." (PMID 33996605, 2021). "Differential diagnoses of other forms of CD5-expressing small-cell lymphomas, such as mantle cell lymphomas and small lymphocytic lymphomas, should be made." (PMID 34814897, 2021). "Patients with CD5-expressing lymphomas presenting with splenomegaly are frequently diagnosed with chronic lymphocytic leukemia." (PMID 34898558, 2021).
Chronic lymphocytic leukemia (continued). "Flow cytometric immunophenotyping of peripheral blood lymphocytes confirmed the presence of 94.5% (19,781/μl) CD19+ B cells, 87.6% of them beating the T cell marker CD5+, aberrantly and commonly expressed in B cell chronic lymphocytic leukemia." (PMID 33942541, 2021). "Chronic lymphocytic leukaemia (CLL) is characterised by the clonal expansion of mature CD19+CD23+CD5+ B-cells in the blood, bone marrow and lymphoid tissue." (PMID 34638404, 2021). "The expression of CD5 on B-cell neoplasms is classically indicative of chronic lymphocytic leukemia (CLL), an indolent neoplasm, or mantle cell lymphoma (MCL), a usually aggressive lymphoma." (PMID 34898558, 2021). "In an Eμ-TCL1 mouse model of chronic lymphocytic leukemia, it was described that Wnt16, Wnt10a, Fzd1 and Fzd6 are pronounced increased in CD5+ B cells." (PMID 33659046, 2021). "Chronic lymphocytic leukemia (CLL) is a heme malignancy characterized by the presence of CD5+ CD19+ B cells in the blood, bone marrow, and lymph node organs." (PMID 34187466, 2021). "CD5 is a membrane surface receptor expressed by thymocytes, mature T cells, B1a subset of B cells, and leukemic B cells of chronic lymphocytic leukemia (B-CLL) disease." (PMID 34222027, 2021). "Chronic lymphocytic leukemia (CLL) is characterized by the accumulation of mature monoclonal CD5+ B lymphocytes in the secondary lymphoid organs, bone marrow and peripheral blood." (PMID 34276674, 2021). "This notion has been challenged by the reported finding that CD5+ chronic lymphocytic leukemia (CLL) cells and their CD5+ B cell progenitors highly express LCK." (PMID 33936048, 2021). "Chronic lymphocytic leukemia (CLL) is a mature B-cell lymphoid neoplasm characterized by the presence of a clonal population of CD5+, CD19+ and CD23+ B-cell lymphocytes accumulating in the peripheral blood, bone marrow, lymph nodes and/or spleen." (PMID 32709095, 2020). "Chronic lymphocytic leukemia (CLL) is characterized by the progressive expansion of B lymphocytes CD5+/CD23+ in peripheral blood, lymph-nodes, and bone marrow." (PMID 30642077, 2019). "CXCL13 and CCL19 together can inhibit the TNFα-mediated apoptosis of the CD23+ CD5+ B cell lineage, which is the commonest malignant cell type in acute and chronic lymphocytic leukemia." (PMID 30819249, 2019). "Chronic lymphocytic leukemia (CLL) is a malignancy characterized by the accumulation of cluster of differentiation 19 (CD19)+ CD5+ B cells in blood, lymph nodes, and bone marrow." (PMID 31484424, 2019). "These authors also indicate that STAT3 phosphorylation on Ser727 in chronic lymphocytic leukemia (CLL) is more elaborate since it requires the assembly of a CK2/CD5/B-Cell Linker Protein (BLNK)/STAT3 complex." (PMID 29464030, 2018). "Chronic lymphocytic leukemia (CLL) is characterized by the accumulation of CD5+, CD19+, CD23+ neoplastic small B cells in secondary lymphoid tissues and peripheral blood." (PMID 29432497, 2018). "The 2008 World Health Organization classification defines chronic lymphocytic leukemia (CLL) as a low-grade lymphoproliferative neoplasm with ≥5 × 109/L clonal B-cells in the peripheral circulation that express CD5, CD19, dimCD20, and CD231." (PMID 30283014, 2018). "Chronic lymphocytic leukemia is the most common adult leukemia characterized by the clonal expansion of malignant CD5+CD19+ B cells." (PMID 28512625, 2017). "Chronic lymphocytic leukemia (CLL) is characterized by the progressive accumulation of clonal CD5+ B cells in lymphoid tissues and peripheral blood." (PMID 29146966, 2017). "Chronic lymphocytic leukemia is the most common form of leukemia in the United States and is characterized by proliferation of CD5+ B cells in bone marrow, peripheral blood, and lymphoid tissues." (PMID 28265553, 2017). "Chronic lymphocytic leukemia (CLL) is a malignancy of CD5+ B lymphocytes that accumulate in the blood, bone marrow and secondary lymphoid tissues such as lymph nodes." (PMID 29262536, 2017).